GRK2 (G protein-coupled receptor kinase 2)
Description:
Specifically phosphorylates the activated forms of G protein-coupled receptors. Such receptor phosphorylation initiates beta-arrestin-mediated receptor internalization, and signaling events leading to their desensitization. Phosphorylates the agonist-occupied form of the beta-adrenergic and closely related receptors, probably inducing a desensitization of them. Phosphorylates catecholamine-activated ADRB2 to regulate physiological cardiomyocyte contraction rate responses (By similarity). Also phosphorylates ligand-bound C3a and C5a anaphylatoxin receptors (C3AR1 and C5AR1, respectively), leading to receptor desensitization. Positively regulates ciliary smoothened (SMO) signaling pathway by mediating phosphorylation of SMO, facilitating SMO trafficking into the cilium and the stimulation of SMO activity. Also positively regulates SMO signaling by mediating phosphorylation of GPR161, a key inhibitor SMO signaling, promoting ciliary export of GPR161. Key regulator of LPAR1 signaling. Competes with RALA for binding to LPAR1 thus affecting the signaling properties of the receptor. Desensitizes LPAR1 and LPAR2 in a phosphorylation-independent manner. Inhibits relaxation of airway smooth muscle in response to blue light.
Synonyms: ADRBK1; BARK1; BETA-ARK1
Tractability: Small molecule: a structure with a bound ligand is known; a high-quality ligand is known; it has a high-quality binding pocket; it belongs to a druggable protein family. Antibody: its Gene Ontology location is reachable by antibodies, with high confidence; UniProt places it where antibodies can reach, with medium confidence. PROTAC: ubiquitination databases record sites on it; a small molecule that binds it is known.
Target class: AGC protein kinase BARK subfamily; Kinase; Protein Kinase; AGC protein kinase GRK family; AGC protein kinase group; Enzyme
Chemical probes: PD080879, PD081169, PD081570, PD081909, PD082654, PD085026, PD085103, PD085343
Safety:
Unwanted effects reported when the protein is acted on. In parentheses: how it was acted on, where the effect was seen, and who reports it.
heart disease (cardiovascular system; source: Force et al. (2011))
Gene: Protein-coding gene on chromosome 11 (67,266,391 to 67,286,557, forward strand). Ensembl gene ENSG00000173020.
Subcellular location: Cytoplasm; Cell membrane; Cell projection, cilium membrane; Postsynapse; Presynapse
Subcellular location (Human Protein Atlas): Vesicles; Cytosol; Golgi apparatus
Pathways (Reactome):
Signal Transduction: Activation of SMO; Calmodulin induced events; G alpha (q) signalling events; G alpha (s) signalling events
Vesicle-mediated transport: Cargo recognition for clathrin-mediated endocytosis
Gene Ontology:
Molecular function: beta-adrenergic receptor kinase activity; Edg-2 lysophosphatidic acid receptor binding; G protein-coupled receptor kinase activity; protein binding; protein kinase activity; alpha-2A adrenergic receptor binding; G protein-coupled receptor binding; ATP binding; protein serine/threonine kinase activity
Biological process: cardiac muscle contraction; desensitization of G protein-coupled receptor signaling pathway; intraciliary retrograde transport; negative regulation of protein localization to ciliary membrane; negative regulation of relaxation of smooth muscle; negative regulation of striated muscle contraction; negative regulation of the force of heart contraction by chemical signal; positive regulation of intraciliary retrograde transport; positive regulation of smoothened signaling pathway; receptor internalization; symbiont entry into host cell; tachykinin receptor signaling pathway; viral genome replication; G protein-coupled acetylcholine receptor signaling pathway; G protein-coupled receptor signaling pathway; positive regulation of catecholamine secretion; regulation of the force of heart contraction; signal transduction
Cellular component: cytoplasm; cytoplasmic side of mitochondrial outer membrane; cytosol; membrane; non-motile cilium membrane; cilium; plasma membrane; postsynapse; presynapse; ciliary membrane
Genetic constraint (gnomAD): Loss-of-function variants: 19 observed, 96.26 expected, observed/expected ratio (o/e) 0.2, 90% interval 0.14 to 0.29. The upper end of that interval is the gene's LOEUF score, 0.29, which puts it in group 1 of 6, group 1 being the genes least tolerant of losing a copy. Missense variants: 573 observed, 920.33 expected, observed/expected ratio (o/e) 0.62, 90% interval 0.58 to 0.67. Synonymous variants: 380 observed, 359.4 expected, observed/expected ratio (o/e) 1.06, 90% interval 0.97 to 1.15.
Homologues: Orthologues: chimpanzee GRK2 (100% identical), macaque GRK2 (99% identical), mouse Grk2 (99% identical), rat Grk2 (98% identical), dog GRK2 (98% identical), guinea pig GRK2 (96% identical), pig GRK2 (94% identical), Drosophila melanogaster Gprk1 (66% identical), Caenorhabditis elegans grk-2 (66% identical), Drosophila melanogaster Gprk2 (30% identical), Caenorhabditis elegans grk-1 (28% identical). Paralogues in human: GRK3 (84% identical), GRK6 (32% identical), GRK5 (32% identical), GRK4 (30% identical), GRK1 (27% identical), GRK7 (26% identical), RSKR (14% identical).
Diseases named in the same sentence as GRK2 in open-access papers:
GRK2 is named in the same sentence as 172 diseases in open-access papers, as found by Europe PMC text mining. Sharing a sentence is not in itself a finding about the gene and the disease. The quoted sentences say what the papers report.
heart failure (79 papers, 2009 to 2026). Inability of the heart to pump blood at an adequate rate to meet tissue metabolic requirements. "Dysregulated GRK2 expression has been implicated in cardiovascular diseases, particularly heart failure, where its upregulation contributes to impaired β-adrenergic signaling and reduced cardiac responsiveness to catecholamines." (PMID 40001594, 2025). "In support of this assertion, elevated myocardial and lymphocyte GRK2 expression and activation have been associated with heart failure." (PMID 38389037, 2024). "As such, GRK2 is now implicated as playing a role in the molecular pathogenesis of a broad group of diseases including heart failure, cancer, depression, neurodegenerative disease, and others." (PMID 33546162, 2021). "The G-protein coupled receptor kinase 2 (GRK2) regulates the desensitization of beta-adrenergic receptors (β-AR), and its overexpression has been implicated in heart failure." (PMID 31506468, 2019). "Together these experiments reveal that RKIP sensitizes the heart failure-promoting AT1 receptor whereas endogenously expressed GRK2 and the kinase-deficient GRK2-K220R mutant inhibit AT1-stimulated signaling." (PMID 30687708, 2018). "The increase in protein activity and upregulation of G-protein coupled receptor kinase 2 (GRK2) is a hallmark of cardiac stress and heart failure." (PMID 28759639, 2017). "Together, these studies suggest the therapeutic potential of targeting hyperinsulinaemia and the Gβγ‐independent GRK2 signalling pathway in heart failure associated with diabetes." (PMID 27983752, 2017). "GRK2 has an important role in the GPCR desensitization process, and abnormally elevated GRK2 protein level is linked with multiple pathological conditions in humans, including myocardial infarction, heart failure and portal hypertension." (PMID 27462452, 2016). "GRK2’s presence in cardiac tissue and its influence on cardiac function, β-adrenergic signaling, and myocardial remodeling underlies its involvement in cardiovascular diseases such as heart failure and ischemia." (PMID 40076919, 2025). "Its overexpression has been associated with heart failure, suggesting that targeting GRK2 could be a therapeutic strategy." (PMID 40244017, 2025). "The β-adrenergic receptor kinase ADRBK1/GRK2, a hallmark of cardiac stress and heart failure, was also highly and selectively phosphorylated in the COV PBMCs, suggesting that GRK2 may contribute to cardiac dysfunction associated with COVID-19." (PMID 38389037, 2024). "The pivotal role of GRK2 in the pathophysiology of heart failure and the diagnostic possibilities it may offer in the future are also highlighted." (PMID 37189604, 2023). "Moreover, the expression of the G-protein-coupled receptor kinase 2 (GRK2) is increased and linked to the progression of heart failure." (PMID 38139099, 2023). "Some experiments suggest that diminished GRK2 activity may act synergistically with β-blocker therapeutic drugs to prevent mortality risk in individuals with heart failure." (PMID 33740423, 2021). "Indeed, GRK2 expression in peripheral lymphocytes of patients with heart failure correlates with kinase levels in the heart and is associated with myocardial failure." (PMID 33467677, 2021). "The relationships between various parameters and the phase plane can be used to investigate changes to cellular signaling akin to those that occur early in heart failure, which is associated with both chronic elevation of resting catecholamines and enhanced activity of GRK2." (PMID 33740423, 2021). "However, hypertension and heart failure are associated withincreased expression and activity of Grk2, which are initially linked to theprevention of excessive β-adrenergic stimulation." (PMID 31034522, 2019).
heart failure (continued). "Interestingly the level of GRK2 is associated to the degree of heart failure, suggesting an importance of GRKs as a heart failure progression biomarker." (PMID 24409150, 2014). "Moreover, during heart failure GRK2 is up-regulated in the adrenal medulla, causing α2-adrenoceptor dysfunction and catecholamine hypersecretion." (PMID 24265619, 2013). "GRK2 levels in myocardium and lymphocytes may be associated with β-AR dysfunction and heart failure severity." (PMID 20204079, 2009). "miR-181a-mediated GRK2 inhibition represents a potential therapeutic strategy for mitigating pathological signaling in heart failure." (PMID 42099781, 2026). "GRK2 is known to translocate to mitochondria in stress models, such as heart failure, where its reduction enhances ATP production and fatty acid utilization." (PMID 40666930, 2025). "AAV6-mediated delivery of βARKct, a peptide inhibitor targeting GRK2, has preserved β-adrenergic responsiveness in post-MI heart failure models." (PMID 41179895, 2025). "Pharmacological inhibition of GRK2 has emerged as a promising therapeutic strategy for heart failure, with inhibitors showing potential in restoring β-AR function and improving cardiac output." (PMID 40001594, 2025). "Although preclinical studies introducing GRK2 inhibitors in heart failure animals models showed improved cardiac functions, but clinical trial didn't show positive outcomes." (PMID 41179895, 2025). "While in chronic conditions, such as heart failure, the increase of GRK2 affects cardiac function, in the acute setting as hypoxia, the kinase displays a different role." (PMID 40659632, 2025). "GRK2 upregulation can exacerbate cardiac ischemia; moreover, elevated kinase levels occur in the early stages of heart failure (HF) and in hypertensive individuals." (PMID 39438268, 2024). "GRK2 and GRK5 have common functions implicated in the regulation of heart failure, though GRK5 has also been involved in diseases like hypertension, cancer, diabetes and Alzheimer's disease." (PMID 39438268, 2024). "GRK2 phosphorylates cardiac β2-adrenergic receptor and increases Gi-biased signaling, which contributes to heart failure." (PMID 38961282, 2024). "A functional GRK2 SNP which inhibits its activity potentiates β-adrenergic receptor-mediated cAMP accumulation and potentially can be used in the treatment of heart failure." (PMID 38961282, 2024). "GRK2 was suggested as a therapeutic target for heart failure, as its genetic inhibition initiated heart protection of adverse remodeling." (PMID 37239897, 2023). "Recent studies have also reported that PRTX as a GRK2 inhibitor capable of preserving cardiac function and decreasing remodeling in acute myocardial infarction and heart failure." (PMID 37815883, 2023). "In support of this statement, Tg-RKIP hearts with symptoms of heart failure showed upregulation of Grk2, which reflects sensitised β-adrenoceptor-stimulated cAMP signalling." (PMID 35203304, 2022). "Taken together, the hearts of Tg-RKIP mice show upregulation of Grk2 and Grk5 and thereby resemble heart specimens of human patients with heart failure." (PMID 35203304, 2022). "G-protein coupled receptor (GPCR) kinase 2 (GRK2) is upregulated in heart failure (HF) patients and mouse models of cardiac disease." (PMID 35269919, 2022). "KRX29 is a small cyclic peptide with potential pathological effects in the treatment of heart failure, which is an effective and selective G protein-coupled receptor kinase 2 (GRK2) activity inhibitor." (PMID 36545472, 2022). "GRK2 inhibition is considered to be cardioprotective under conditions of exaggerated GRK2 activity such as heart failure." (PMID 35203304, 2022). "For instance, an exaggerated GRK2 activity contributes to symptoms of cardiovascular diseases such as heart failure and hypertension." (PMID 35203304, 2022).
heart failure (continued). "During the pathogenesis of heart failure, there is an upregulation of GRK2-Grk2, which accounts for the impaired contractile reserve of failing hearts by desensitisation and downregulation of cardiac β-adrenoceptors." (PMID 35203304, 2022). "This review aims to delineate how the multifunctional protein and GRK2 inhibitor RKIP accounts for a heart failure phenotype despite cardioprotective signalling stimulated by GRK2 inhibition." (PMID 35203304, 2022). "This is the reason why paroxetine-mediated direct inhibition of GRK2 has been reported to be fruitful in mice studies for improving osteoarthritis, cardiac hypertrophy, myocardial infarction, and heart failure." (PMID 36275707, 2022). "Inhibition of GRK2 by RKIP sensitises the heart failure-promoting AGTR1-Agtr1, which triggers cardiac fibrosis." (PMID 35203304, 2022). "In heart failure for example, the upregulation of GRK2 and GRK5 leads to the downregulation and desensitization of the beta adrenergic receptors." (PMID 35163118, 2022). "Since increased Adipoq and Ucp1 levels contribute to heart failure pathogenesis, the Grk2 inhibition-induced normalisation of pathologically elevated Adipoq and Ucp1 levels is a desired, positive therapeutic effect and not an adverse effect." (PMID 35203304, 2022). "Inhibition of pathologically elevated GRK2 by different approaches, gene transfer and gene knockout showed beneficial effects in many models of cardiac dysfunction and heart failure." (PMID 35203304, 2022). "Comparison between C and F represents the case where β-blockers reduce β1-AR availability and inhibit GRK2, compensating for kGRK2 upregulation in early heart failure." (PMID 33740423, 2021). "Here, we will discuss the recent findings on the metabolic role of GRK2 in insulin resistance-related conditions, such as diabetes, hypertension, and heart failure." (PMID 33467677, 2021). "Accordingly, inhibition of GRK2 is considered an important drug target in the treatment of heart failure." (PMID 33562229, 2021). "In other pathological contexts, GRK2 is a very relevant signalling hub, such as in heart failure, where GRK2 protein expression levels are increased at late stages after myocardial infarction but are decreased early after ischaemia." (PMID 33466410, 2021). "With NE levels corresponding to the elevated baseline used to simulate early heart failure, the joint treatment of β-blockers with GRK2 downregulation reduces the overshoot amplitude (1.18 μM cAMP) for a fixed dynamic range of 0.26 μM cAMP." (PMID 33740423, 2021). "The genetic deletion or pharmacologic inhibition of GRK2 confers protection against heart failure, cardio-metabolic dysregulation, and vascular dysfunction." (PMID 33803070, 2021). "The inhibition of GRK2 has been studied extensively in vivo; however, evidence of its impact on heart failure remains scarce." (PMID 35155607, 2021). "Specifically, enhanced GRK2 expression has been reported in the failing human hearts and in experimental models of heart failure, in both chronic hypertensive, and ischemic disease." (PMID 35386975, 2021). "While β-blockers competitively inhibit β1-ARs, GRK2 has recently been proposed as an additional therapeutic target in heart failure." (PMID 33740423, 2021). "Studies of animal models have shown that reducing GRK2 levels is beneficial in preventing heart failure by renormalizing catecholamine and βAR levels of cell surfaces and improving heart function." (PMID 33562229, 2021). "While regulation of stability seems to be the main pathway controlling GRK2 dosage, changes in mRNA transcription have also been reported in several pathological conditions, including hypertension, cardiac hypertrophy, and heart failure." (PMID 30837878, 2019). "GRK2 has a relevant role in the control of cardiac function and enhanced GRK2 expression has been reported in the failing human hearts and in experimental models of heart failure (HF) in contexts of both chronic hypertensive and ischemic disease." (PMID 30837878, 2019).